INS (insulin)
Diseases named in the same sentence as INS in open-access papers (continued):
Sharing a sentence is not in itself a finding about the gene and the disease.
hyperandrogenism (continued). "Anita Verma’s study also reported a potentially significant decrease in menstrual irregularity, clinical hyperandrogenism, fasting blood glucose, fasting insulin, and HOMA-IR values." (PMID 39054488, 2024). "Research suggests that metformin can effectively enhance insulin sensitivity and appears to mitigate insulin-mediated androgen production, alleviating hyperandrogenism in PCOS patients and improving ovarian function." (PMID 38665877, 2024). "Within the ovaries, insulin collaborates with LH to stimulate androgen production in the ovarian cells, and exacerbate hyperandrogenism." (PMID 39376609, 2024). "High insulin stimulates more ovarian androgen production — leading to worsened symptoms of hyperandrogenism — and inhibits the release of fatty acids from cells." (PMID 39516828, 2024). "Vitamin E has been investigated for its ability to reduce oxidative stress, improve insulin sensitivity and potentially ameliorate some of the symptoms associated with PCOS, such as irregular menstrual cycles and androgen excess." (PMID 38817374, 2024). "Women with PCOS who exhibit hyperandrogenism, high BMI, and IR have diminished metabolic flexibility (as determined by changes in respiratory quotient following insulin stimulation)." (PMID 38571924, 2024). "Canagliflozin and metformin exert no different outcomes from metformin monotherapy in weight control, insulin sensitivity, androgen excess, and menstrual frequency." (PMID 38500709, 2024). "The IGF receptors’ overactivity leads to higher production of ovarian androgens, as insulin maintains its action on the ovary, resulting in clinical hyperandrogenism in women with T2DM." (PMID 38353886, 2024). "Despite affecting fertility, PCOS is identified by elevated levels of AMH due to insulin actions in granulosa cells, which are marked by hyperandrogenism." (PMID 39336427, 2024). "Circulating insulin can also activate ovarian stromal cells and granulosa cells to produce excess androgens, which are responsible for the symptoms of hyperandrogenism." (PMID 37569402, 2023). "Although the reduction in insulin-stimulated glucose uptake in women with hyperandrogenism is primarily due to skeletal muscle insulin resistance, other tissues, such as the endometrium, also contribute to systemic insulin resistance." (PMID 37371678, 2023). "The etiology of PCOS is multifaceted, involving various genetic and epigenetic factors, hypothalamic–pituitary–ovarian dysfunction, androgen excess, insulin resistance, and adipose-related mechanisms." (PMID 37432488, 2023). "The high concentration of insulin can regulate the production of free testosterone and lead to hyperandrogenism through the increase of free insulin‐like growth factor I (IGF‐I) and sex hormone‐binding globulin (SHBG)." (PMID 37823091, 2023). "In PCOS rat models, treatment with Lactobacillus and FMTs improved hyperandrogenism and influenced insulin function." (PMID 36835989, 2023). "This is unsurprising given the well-recognised clinical features and subsequent risk factors associated with PCOS, including menstrual dysfunction, infertility, hyperandrogenism; glucose and insulin dysfunction; T2DM; and cardiovascular disease." (PMID 38137570, 2023). "Oxidative stress triggers a state that is pro-inflammatory and leads to both hyperandrogenism and insulin resistance in a feedback loop." (PMID 36979879, 2023). "As previously discussed, factors such as insulin signaling and IR are involved in androgen excess and in the development of hyperandrogenism." (PMID 37047186, 2023). "Rather than a function of direct androgenic action only, effects from hyperandrogenism on fetal development and pregnancy outcomes are potentially mediated by insulin and further altered by hyperinsulinemic states." (PMID 36733795, 2022). "Metformin is the first line drug to improve insulin sensitivity and decrease insulin contribution to hyperandrogenism in PCOS patients." (PMID 35881588, 2022).
hyperandrogenism (continued). "Overweight/obese compared to normal-weight women with PCOS exhibit greater preferential abdominal fat accumulation, hyperandrogenism and insulin resistance accompanied by increased serum glycerol levels from impaired insulin suppression of lipolysis." (PMID 35012577, 2022). "Previously, skin fibroblasts were for the intrinsic problems in in insulin function in PCOS because both hyperandrogenism and hyperinsulinaemia affect insulin sensitivity." (PMID 35356614, 2022). "Women with vaginal bleeding intervals of longer than 45 days who had hyperandrogenism (HA) showed a higher level of glucose, insulin, HOMA-IR, and HOMA-β but lower QUICK I and Matsuda Index." (PMID 35769085, 2022). "The increase in insulin level can up-regulate androgen levels, thereby inducing hyperandrogenism and up-regulating androgen levels in fatty tissues of PCOS patients via increased AKR1C3 activity." (PMID 36465612, 2022). "Hyperandrogenism in PCOS is thought to be related to increased levels of androgen production by insulin and an upregulation of insulin-like growth factor (IGF-1) receptors." (PMID 35052471, 2022). "Taken together, the results from these clinical studies suggest that chronic insulin treatment can mimic the hyperandrogenism, anovulation and ovarian morphology of PCOS, but through different pathophysiological mechanisms than PCOS." (PMID 35269778, 2022). "Different forms of fasting, such as intermittent fasting and regular fasting, can lower glucose and insulin levels, which can have beneficial effects on ovarian function, androgen excess, and infertility in women with PCOS." (PMID 36060969, 2022). "They reported that serum total cholesterol, insulin, HOMA-IR, hyperandrogenism, ALT, and AST are factors associated with NAFLD, but after multiple regression analyses, only HOMA-IR and hyperandrogenism were significant predictors of NAFLD." (PMID 35052811, 2022). "We observed a decreased insulin sensitivity and hyperandrogenism in women with GDM compared with women with NGT." (PMID 36440200, 2022). "In this review, we discuss some controversial diagnostic and therapeutic aspects of PCOS, such as the role of insulin resistance, inflammation, and hyperandrogenism." (PMID 35456928, 2022). "Although, the precise nature of the role of reproductive genes associated in this study cannot be readily discerned, they possibly manifest T2DM through hyperandrogenism and defects in insulin secretion." (PMID 34784930, 2021). "Myo-inositol (MI) increases insulin sensitivity, decreases hyperandrogenism and improves the menstrual cycle." (PMID 33468143, 2021). "Metformin hydrochloride (MH) is commonly used as an insulin sensitizer to restore the elevated insulin and androgens levels and BMI; clomiphene citrate, developed as antiandrogens, is another way to resolve hyperandrogenism." (PMID 33299379, 2020). "Hyperandrogenism induced by DHEA is associated with a greater number of apoptotic cells in the endometria, and metformin (an insulinomimetic or insulin-sensitizing agent) is able to reduce the increased number of apoptotic cells." (PMID 32903374, 2020). "Targets for pharmacological treatment include biochemical and clinical androgen excess, menstrual irregularities, anovulation, insulin resistance, and metabolic profile." (PMID 32849300, 2020). "In a randomized placebo-controlled trial on 40 premenopausal women, pioglitazone was more effective than placebo in improving insulin sensitivity, hyperandrogenism, and ovulation rate." (PMID 33334002, 2020). "Decreased levels of insulin, total and bioavailable T led to significant improvement of hyperandrogenism." (PMID 33255783, 2020). "The androgenic enzyme aldoketoreductase type 3 (AKR1C3) is expressed in subcutaneous adipose tissue and is stimulated by insulin to contribute to hyperandrogenism in obese women." (PMID 31616381, 2019).
hyperandrogenism (continued). "Different fasting regimens can reduce IGF-1, IGFBP1, glucose, and insulin levels and consequently have beneficial effects on ovarian function, androgen excess, and infertility in women with PCOS." (PMID 31603907, 2019). "Apart from an improvement in hyperandrogenism and insulin sensitivity, orlistat supposedly increases serum anti-müllerian hormone (AMH) levels in obese PCOS patients." (PMID 29344438, 2017). "Combined statins and metformin therapy can improve lipid and inflammation parameters, but cannot effectively improve insulin sensitivity and hyperandrogenism in women with PCOS, when compared to metformin alone." (PMID 29344438, 2017). "We studied a patient whose case demonstrated that gonadotropins are required ascofactors for insulin-induced hyperandrogenism in type B insulin resistance." (PMID 27911591, 2017). "Pharmacologic reduction in insulin levels by either metformin or thiazolidinediones ameliorates both hyperinsulinemia and hyperandrogenism." (PMID 27635134, 2016). "In the present study, SES scores were positively correlated with fasting insulin and total testosterone levels in AN obese girls with hyperandrogenism." (PMID 25800478, 2015). "Statins alone or combined with metformin cannot effectively improve insulin sensitivity and reduce hyperandrogenism." (PMID 25818277, 2015). "Women with oligo-anovulation (O) and PCO morphology (P) had a significantly lower level of 2-h postprandial insulin compared to women with O, P and hyperandrogenism (H) phenotypes." (PMID 25595199, 2015). "Combined statin and metformin therapy can improve lipid and inflammation parameters, but cannot effectively improve insulin sensitivity and reduce hyperandrogenism in women with PCOS." (PMID 25818277, 2015). "The use of drugs such as metformin, which improves insulin sensitivity and decreases resistance to this hormone, has had good results in some studies with the decrease of high insulin levels and improvement of hyperandrogenism." (PMID 22778733, 2012). "Hyperandrogenism is optimally dealt with by reducing insulin drive to the ovary, with measures such as exercise and diet modification." (PMID 19562048, 2008). "In 1991, Poretsky and Nestler found insulin to be an effector of ovarian and adrenal steroid metabolism, and postulated the paradox of insulin-induced hyperandrogenism within insulin-resistant states." (PMID 16603055, 2006). "This integrated perspective recontextualizes the roles of insulin, inflammatory mediators, and genetic variants as direct effectors of follicular distress, not merely as upstream triggers of androgen excess." (PMID 42096403, 2026). "Furthermore, fecal microbiota transplantation (FMT) from inulin‐treated patients with PCOS enhanced insulin sensitivity, improved lipid accumulation and thermogenesis, reduced hyperandrogenism and ovarian inflammatory response in antibiotic‐treated mice." (PMID 40192074, 2025). "This specific effect of aerobic exercise on hyperandrogenism is strongly supported by mechanistic insights suggesting improvements in insulin sensitivity, which is a key factor in the syndrome's pathophysiology and directly influences ovarian androgen production." (PMID 41586011, 2025). "Such interventions could include more aggressive luteal phase support for hyperandrogenism or the adjunctive use of insulin-sensitizing agents like metformin for significant metabolic dysregulation." (PMID 41585786, 2025). "Moreover, reduced insulin sensitivity inevitably results in hyperinsulinemia, which in turn fosters the development of hyperandrogenism by exerting a chronic stimulus on the cells of the ovarian theca." (PMID 40650016, 2025). "Elaborating further, LPC 16:0 was the only LPC with lower values in both lean and obese PCOS vs controls, suggesting that this downregulation could be related to hyperandrogenism with androgen overriding the stimulatory effects of insulin." (PMID 40157992, 2025).
hyperandrogenism (continued). "The normalization of androgen levels following bilateral oophorectomy may have contributed to improved glycemic control, underscoring the role of androgen excess in insulin resistance, in conjunction with pharmacotherapy and lifestyle measures." (PMID 40443457, 2025). "Various explanations are proposed in the literature to understand the effect of PCOS on oocyte quality, such as insulin resistance, hyperandrogenism, increased oxidative stress and impaired mitochondrial energy metabolism, chronic inflammatory state, and lipid disturbances." (PMID 39797326, 2025). "Furthermore, there is evidence that hyperandrogenism in combination with an HFD disrupts insulin sensitivity." (PMID 40563843, 2025). "Conversely, hyperandrogenism damages hepatic and peripheral insulin sensitivity." (PMID 38846566, 2024). "These lowered insulin levels may decrease androgen production and hyperandrogenism symptoms in women with PCOS." (PMID 39516828, 2024). "By enhancing the overall quality of life through the restoration of regular menstrual cycles, reduced hyperandrogenism, improved insulin sensitivity, and fertility enhancement, melatonin offers hope for a brighter future for those affected by this challenging syndrome." (PMID 38106751, 2023). "This supports the idea that it is not hyperandrogenism per se that has a causal relationship with cardiovascular risk factors, and it highlights the key role of insulin in regulating these factors." (PMID 37629271, 2023). "However, HIIT has shown to offer greater improvements in aerobic capacity, insulin sensitivity and menstrual cyclicity and larger reductions in hyperandrogenism compared with moderate intensity training." (PMID 37048550, 2023). "Hyperandrogenism can lead among others to rapid postnatal growth, advanced bone age, and premature pubarche in childhood, as well as acne, hirsutism, menstrual irregularities (in females), and decreased insulin resistance in adulthood." (PMID 36578966, 2022). "As such, effects of hyperandrogenism on fetal development and pregnancy outcomes could be mediated via insulin and further altered by the impact of hyperinsulinemic states." (PMID 36733795, 2022). "Considering that androgen excess in women impairs hepatic glucose metabolism by decreasing insulin-stimulated glucose uptake and glycogen synthesis, the MAPK14 pathway may be a nexus between IR and hyperandrogenism that is triggered by oxidative stress." (PMID 36498989, 2022). "Moreover, with excessive weight gain/obesity and a higher body mass index, altered insulin sensitivity can interact with hyperandrogenism to aggravate PCOS phenotypes." (PMID 35881588, 2022). "Similarly, transplantation of BAT into PCOS-like rats restores anovulation and the menstrual cycle, alleviates hyperandrogenism and polycystic ovary morphology, and normalizes systemic insulin sensitivity." (PMID 35436959, 2022). "Besides hyperandrogenism, also glucocorticoids lead to insulin resistance by opposing the actions of insulin." (PMID 36578966, 2022). "In turn, insulin increases ovarian androgen synthesis aggravating hyperandrogenism." (PMID 33095902, 2021). "Hyperandrogenism women usually occur after an increase in insulin." (PMID 34330312, 2021). "The abnormal increase of insulin could stimulate the oversecretion of androgen, thus inducing hyperandrogenism." (PMID 33299379, 2020). "However, it is important to note that the specific features of each patient (PCOS, hyperandrogenism, GDM, low adherence to insulin, risk of preeclampsia) are important to consider when estimating the risk/benefits ratio." (PMID 32625081, 2020). "Hyperandrogenism is also reported to induce an excessive release of insulin by pancreatic β-cells." (PMID 32917200, 2020).
hyperandrogenism (continued). "In concert, these studies provide a possible linkage for tissue-specific defects contributing to PCOS-like metabolic phenotype, including hyperandrogenism-mediated, adipogenic constraint, that likely promotes insulin resistance and pancreatic β-cell defects through lipotoxicity." (PMID 32310267, 2020). "Briefly, insulin is considered as a key hormone for hyperandrogenism in the PCOS pathophysiology via two different pathways: 1) insulin stimulates androgen production of theca cells with luteinizing hormone (LH) and elevated androgen production leads to hirsutism, acne, and anovulatory infertility." (PMID 30299265, 2018). "In fact, increased insulin levels are an important factor for the maintenance of hyperandrogenism." (PMID 29490689, 2018). "Additionally, insulin has been shown to lower sex hormone binding globulin, which can lead to increased free androgen levels and clinical hyperandrogenism." (PMID 28620546, 2017). "Second, interventions that increase insulin sensitivity improve, independent of weight loss, ovulatory function, menstrual cyclicity, fertility, and hyperandrogenism in lean and obese patients." (PMID 27375552, 2016). "Furthermore, insulin also influences hyperandrogenism by inhibiting liver synthesis of SHBG2 and IGFBP-1, which binds IGF-1 IGF-1 is a growth factor with endocrine action." (PMID 27423183, 2016). "Insulin sensitizers improve menstrual regularity and hyperandrogenism." (PMID 27375552, 2016). "Insulin may lead to hyperandrogenism by reducing SHBG production in the liver and also by increasing the amount of circulating free testosterone, a biologically active androgen." (PMID 26761944, 2016). "The PCOS group had higher testosterone levels and hyperandrogenism, both of which could potentially modulate both insulin sensitivity and brain glucose metabolism." (PMID 26650926, 2015). "However, toreach a better understanding of PCOS pathophysiology,more studies are warranted in whichPCOS patients are grouped based on their BMI,insulin and androgen levels, presence of clinicalfeatures of hyperandrogenism, and severityof polycystic ovaries." (PMID 25493169, 2012). "Consequently, increased systemic insulin levels result in an increase in insulin-dependent androgen overproduction within ovarian theca cells, thereby creating a vicious circle where IR leads to hyperandrogenism and vice versa." (PMID 39959624, 2025). "In type 1 DM (T1DM), insulin treatment, although it has reduced the rates of insulinopenic-induced hypogonadotropic hypogonadism, an entity commonly presented in many women with the disease in the past decades, when it is used in excess it can also promote hyperandrogenism." (PMID 38353886, 2024). "Consequently, we performed systematic review and meta-analysis with all available RCTs to investigate whether resveratrol can improve menstrual irregularity, and symptoms related to hyperandrogenism and reduce the levels of androgens and insulin." (PMID 37333786, 2023). "A healthy diet can lead to weight loss, improved insulin metabolism, increased regularity of menses, and a reduction in testosterone and cholesterol levels, but these diets have not been effective in treating biochemical hyperandrogenism." (PMID 37510690, 2023). "This study showed that insulin sensitivity and ovarian functions in PCOS were modulated by IL-22-associated browning of white adipose tissue, indicating that IL-22 may help treat PCOS with a hyperandrogenism phenotype." (PMID 36835989, 2023). "Hyperandrogenism in PCOS could be caused by defective intrinsic steroidogenesis in ovarian theca cells or by elevated LH levels due to altered regulation of the hypothalamic–pituitary axis, also influenced by insulin." (PMID 35456928, 2022).